STAT3 (signal transducer and activator of transcription 3)
Diseases named in the same sentence as STAT3 in open-access papers (continued):
Sharing a sentence is not in itself a finding about the gene and the disease.
tumor (continued). "It has also been shown that STAT3 activation in tumor participated in immune suppression on CD8+ T cells, and thus, FM may restore the activity of CD8+ T cells by inhibiting STAT3 activation." (PMID 29784005, 2018). "Thus, Hst, by suppressing the stromal STAT3 activity would also contribute to the tumor inhibition synergy with CPT-11." (PMID 29963254, 2018). "However, there are available a host of chemically synthesized molecules that exhibit promising STAT3 inhibiting activity and, in many cases, can abrogate tumor growth." (PMID 30217007, 2018). "Furthermore, CK inhibited STAT3 DNA-binding activity to regulated STAT3 target genes that are involved in tumor survival and apoptosis." (PMID 29921768, 2018). "Moreover, numbers of researches have shown that STAT3-targetd therapy can effectively inhibit tumor development." (PMID 29423040, 2018). "Moreover, hesperetin was found to impose a tumor inhibition synergy with CPT-11 through suppressing the STAT3 activity and recruiting the tumoricidal macrophages into the microenvironment." (PMID 29963254, 2018). "Furthermore, phosphorylation of STAT3 in xenograft tumor was identified using immunohistochemistry assay." (PMID 29915371, 2018). "Moreover, Hst was found to work synergistically with CPT-11 in tumor inhibition by suppressing the tumor's STAT3 activity and recruiting tumoricidal macrophages into the tumor microenvironment." (PMID 29963254, 2018). "Additionally, inflammatory cytokines within the tumor microenvironment also play crucial roles in the majority of solid tumors by activating the JAK/STAT3 pathway." (PMID 30564118, 2018). "In addition, persistent activation of STAT3 in NK cells and neutrophils inhibit the tumor killing activity of those effector cells." (PMID 28659794, 2017). "Notably, with Ttl, S100a4, Zfx, Cct3, Stat3, Stab1 and Bmx, 7/20 found candidate genes have been reported as proliferation-related in tumor cells too." (PMID 29228606, 2017). "However, in the context of a humanized mice, STAT3 silencing significantly decreased the growth rate of the reconstituted tumor." (PMID 28008146, 2017). "Indeed, the growth of MM, as of other tumors, is mainly due to the effect of tumor-released factors and relays on the constitutive activation of several pro-survival pathways including STAT3." (PMID 28435516, 2017). "Importantly, overexpression of ectopic GPRC5A in HNSCC cells inhibits IL-6-induced STAT3 activation and suppresses the anchorage-independent tumor growth." (PMID 28270740, 2017). "STAT3 has been shown to promote tumor progression, whereas STAT1 tends to suppress it." (PMID 28626343, 2017). "STAT3 is a transcription factor that directly regulates a panel of tumor-promoting genes." (PMID 28503147, 2017). "The disrupted upstream signalling in tumour cultured DCs, including the attenuated canonical NF-κB and STAT3 signalling pathways, may be the key reason." (PMID 28350008, 2017). "Targeting STAT3 for tumor angiogenesis becomes a promising strategy." (PMID 28978186, 2017). "In addition, inhibitors such as α-Solanine and microRNA-539 are demonstrated to be effective inhibitors of STAT3 activity and tumor growth." (PMID 28978186, 2017). "Then, we measured the change of JAK/STAT3/IL-8 signaling pathway in the tumor specimens of mice." (PMID 28967875, 2017). "Thus, repression of GPRC5A has been linked to upregulation of STAT3 signaling pathway in HNSCC, which contributes to tumor progression." (PMID 28270740, 2017). "In addition, most genes in interferon signalling, which is negatively regulated through the STAT3 pathway, showed increased transcription levels in tumour-induced DCs." (PMID 28350008, 2017). "Together with that c-MYC was one of STAT3 target genes, and was essential for tumor angiogenesis, we wondered whether JAK/STAT3 signaling pathway was aberrant activated during the transition of NECs toward TECs." (PMID 29088816, 2017).
tumor (continued). "The following paragraphs describe the molecular mechanisms that, in a simplified view, enable unhindered tumor cell growth, driven by constitutive NFκB and STAT3 signaling, and simultaneously preclude immune cell activation by preventing pro-inflammatory NFκB via STAT3-driven mechanisms." (PMID 28275576, 2017). "Our results suggested that high STAT3 expression in ICC patients may facilitate tumor progression and worsen surgical outcomes by promoting its own phosphorylation." (PMID 28032598, 2017). "In addition, the expression of phospho-STAT3 in the tumor tissues was downregulated by DCZ3301 treatment." (PMID 29022919, 2017). "Besides its normal function, STAT3 has been shown to involve in the tumor development and cell transformation." (PMID 28594363, 2017). "However, high pY-STAT3 was reported to be highly correlated with a better prognosis for some human cancers and Stat3 can function as a tumor suppressor in Apc mice and in K-Ras mice." (PMID 29126425, 2017). "Emerging studies suggest that let-7a may restrain tumor cell proliferation by blocking the STAT3 pathway." (PMID 28187784, 2017). "Moreover, DC maturation is inhibited by the downregulation of the STAT3 pathway mediated by secretion of IL-6 by tumour cells." (PMID 28315228, 2017). "Solute carriers may have a key role in regulating tumour angiogenesis, cell proliferation and STAT3 signalling in cancer and thus, dysregulation of these genes may also have a role in TLR2-induced pro-inflammatory mechanisms." (PMID 28225071, 2017). "R2016 induced apoptotic tumor cell death and anti-tumor favorable immune induction may thus in part be through the inhibition of STAT3 and STAT5 activation." (PMID 28282460, 2017). "Although emerging evidence suggests that STAT3 plays a critical role in EMT and tumor progress, its signaling mechanisms underlying persistent activation of STAT3 associated with EMT-associated CSC-like characteristics remain unclear." (PMID 29254164, 2017). "Interestingly, STAT3 expression in NK cells was increased or decreased in patients with different tumor localization, while the expression of c‐kit and c‐myc was reduced in all patients with cancer in comparison to healthy volunteers." (PMID 28695716, 2017). "Some reports suggested that OSCC tumor cells frequently produce high levels of p-STAT3, and various JAKs and STAT3 inhibitors could abrogate OSCC growth." (PMID 28085115, 2017). "The expression of STAT3 downstream genes (cyclin D1 and Mcl-1) was also detected by real-time quantitative PCR, and samples from Atn-treated mice showed downregulated cyclin D1 and Mcl-1 mRNA expression levels compared with tumor tissues from vehicle mice." (PMID 27861147, 2017). "Considering the important role of IL-11/STAT3 signaling pathway in tumor progression and metastasis, therapeutic options using direct STAT3 inhibitors or upstream inhibitors might be used for the treatment of ccRCC in the future." (PMID 29100303, 2017). "STAT3, as a signal mediator protein, reflects these particular tumor stages through its PTMs." (PMID 28489571, 2017). "Continuous deregulation of these genes in tumor cells and the tumor microenvironment by persistently activated STAT3 and NF-κB, in contrast to their tightly controlled regulation in normal physiology, is considered crucial for inflammation and malignant progression." (PMID 28626726, 2017). "The histogram plot and intensity value also revealed that combination treatment showed a notable decrease in p-STAT3 level compared to the EA alone (384.02 ± 13.36) and thus, depicted EA along with radiation was more effective to tumour cells than radiation or EA alone." (PMID 29070894, 2017). "Moreover, we found that repression of GPRC5A is associated with activated STAT3 in HNSCC, which correlates with tumor progression." (PMID 28270740, 2017).
tumor (continued). "As a downstream regulatory object of EGFR in EGFR-STAT3 oncogenic pathway, aberrantly activated and up-regulated STAT3 signaling pathway has been detected in various cancers including HCC and is considered as an essential risk factor for tumor initiation and development." (PMID 28432618, 2017). "In addition, IL-6, IL-10, and VEGF activate STAT3 in tumor infiltrating immune cells, providing a feed forward mechanism for STAT3 activation in the tumor microenvironment." (PMID 28611673, 2017). "The chemokine CXCL12 is constitutively secreted by bone marrow stroma cells in CLL and binds CXCR4 on the surface of CLL cells to direct chemotaxis, support tumor survival, and activate various signaling pathways, including STAT3 by phosphorylation of its serine 727 residue." (PMID 29379494, 2017). "Moreover, increased STAT3 signalling in dendritic cells inhibited their maturation and subsequent ability to serve as antigen-presenting cells in educating anti-tumour immune responses." (PMID 28276425, 2017). "However, in T cell-mediated anti-tumor immunity, STAT3 activation inhibits immune responses by antagonizing NF-κB and STAT1-mediated expression of T helper 1 (Th1) cytokines." (PMID 28978186, 2017). "Towards the goal of targeting the adaptive immune resistance mechanism of the developing tumor, we and other authors previously noted that tumor cell STAT3 signaling can potentially regulate the leukocytic infiltration into the TME as part of its pleiotropic carcinogenic effects in murine models." (PMID 28008146, 2017). "These raised a question about whether the combination of STAT3 inhibitor and chemotherapy would have greater anti-tumor effects in ASCC mouse model." (PMID 28747781, 2017). "Taken together, it is speculated that STAT3 inhibitory potential of fluspirilene can be a major mechanism of anti-tumor effect in GBM." (PMID 29340087, 2017). "Thus, we draw that QRHX played a more important role in inhibiting tumor growth by regulating TAMs in mice, which was found to be associated with the inhibition of inflammation and the CXCL12/CXCR4/JAK2/STAT3 signaling pathway." (PMID 28630636, 2017). "In addition, using immunohistochemistry (IHC), we also observed that simvastatin treatment increased AMPK phosphorylation, reduced STAT3 phosphorylation and decreased Skp2 expression in tumor tissues." (PMID 28230855, 2017). "As for the attenuated canonical NF-κB and STAT3 signalling in tumour-induced DCs in the model used in the present study, these two pathways may cooperate to promote DC development." (PMID 28350008, 2017). "As GAC 17:1 inhibited phosphorylation of STAT3 which plays an important role in tumor cell proliferation, we next examined whether cell proliferation of U266 and MM1.S cells can also be affected by GAC 17:1." (PMID 28208828, 2017). "Tumor infiltrating myeloid cells undergo a functional change in response to STAT3 activation." (PMID 28197019, 2017). "Persistent STAT3 activation is seen in many tumor cells and promotes malignant transformation." (PMID 27458171, 2017). "The impaired cell migration and tumor invasion could partly be attributed to STAT3 inactivation by OSU-A9." (PMID 28418923, 2017). "Combined, these data suggest that the STAT3 activation status of tumours may dictate whether STAT1 promotes or attenuates anti-tumour immunity, and that the ShcA pathway is an important integrator of this process." (PMID 28276425, 2017). "The cytokines like IL-6 and TNF-α may activate pro-tumor pathways like STAT3 to promote cellular proliferation and thereby initiate carcinogenesis." (PMID 28360909, 2017). "However into 8–9 Gleason we observed also an evident cytoplasmatic presence of pY705-STAT3; in particular this result was directly related to the persistently activated STAT3 which plays an important role in tumor progression and malignancy." (PMID 28489571, 2017). "Thus, STAT3 contributes, in part, to the establishment of an immunosuppressive microenvironment in MT/Shc313F/313F tumours." (PMID 28276425, 2017).
tumor (continued). "Specifically, proinflammatory cytokine IL-6 induces Twist1 expression in normal fibroblasts via STAT3 phosphorylation, and Twist1 then promotes the transdifferentiation of normal fibroblasts to CAFs via activation of a strong tumor-promoting chemokine, CXCL12, as well as suppression of senescence." (PMID 29029429, 2017). "Accumulated evidence indicates that the combination of EGFR TKI with STAT3 inhibitors could be of benefit and increase the anti-tumor activity of these agents." (PMID 28521301, 2017). "However, a growing number of reports also suggest a tumor-suppressive function of STAT3 in some cancers." (PMID 29126425, 2017). "Moreover, Stat3 favors proliferation and maintenance of CSCs, and its inhibition blocks tumor formation in glioblastoma." (PMID 28415725, 2017). "Additionally, intraperitoneal injections of Capz inhibited tumor growth and STAT3 activation in tumor tissues from athymic nu/nu male mice with subcutaneous DU145 xenografts." (PMID 27458171, 2017). "Together, these results reveal an Fbw7-dependent mechanism that regulates Stat3 ubiquitylation and degradation, providing new insight into the tumor suppressor role of Fbw7, and suggesting that Fbw7 may offer a promising new approach to ABC-DLBCL therapy." (PMID 28069035, 2017). "It is possible that the increase in these cytokines in the extracellular media surrounding tumor cells might promote tumorigenesis by activating the NFkB and/or STAT3 pathways." (PMID 28938604, 2017). "Tumor vessels were lined by Stat3+ cells and tumor cells were identified near to the vessel wall." (PMID 28415725, 2017). "Next, we examined the effects of STAT3 on the tumour invasion-promoting effects of ADSCs." (PMID 28423603, 2017). "Activation of STAT3 may prevent death of tumor cells and stimulates tumor proliferation, invasion, and migration." (PMID 29234375, 2017). "Thus, high STAT3 expression was an indication of more lymph node metastasis and increased tumor burden in vivo and in vitro." (PMID 28032598, 2017). "In addition, immunohistochemistry of NC-treated HSC3 tumor xenografts showed that the expression levels of phosphorylated STAT3 were significantly reduced in NC-treated tumors at the protein level." (PMID 29207645, 2017). "STAT3 activation promotes survival and prevents tumour cell apoptosis in numerous cancer types." (PMID 28186993, 2017). "STAT3 supports tumor survival, proliferation, and invasion and can lead to immunosuppression." (PMID 28792479, 2017). "The possible potential mechanisms for REGIA activity included: First, REGIA expression may inhibit the tumor cell apoptosis through acceleration of STAT3 and Bcl-2 expression." (PMID 29162157, 2017). "EC-derived IL-6 induces phosphorylation of STAT3 in tumor cells and promotes tumor growth." (PMID 28978186, 2017). "STAT3 inhibitor has effects on both tumor and immunocytes that converge to mediate tumor rejection." (PMID 28747781, 2017). "Considering the well-known effect of IL-6 on STAT3 activation and the presence of IL-6 in our tumor model, we next asked whether IL-6 produced by TAMs contributes to the proliferative advantage provided by macrophages in our co-culture system." (PMID 29207662, 2017). "Thus, we consolidate the idea that the inactivation of genes regulating the JAK/STAT3 pathway can support tumor expansion through the repression of JAK/STAT signaling." (PMID 28369102, 2017). "These tumor-suppressive activities of GRIM-19 may be attributed to its inhibitory role in the function of STAT3." (PMID 28443075, 2017). "We confirmed SH003 inhibition of tumor growth by repressing STAT3 activation." (PMID 29179443, 2017). "Previous studies revealed that activation of STAT3 promotes tumor angiogenesis." (PMID 28978186, 2017). "Targeting either TRIM8 or STAT3 could effectively disrupt the positive feedback loop and attenuate the self‐renewal capacity and tumor propagation of GBM." (PMID 28100038, 2017).
tumor (continued). "Tumorigenic potential of cells with activated mTOR signaling are suppressed by NOTCH inhibition, which indicate that the STAT3/p63/NOTCH axis may serve as a target for the treatment of tumor with hyperactive mTOR signaling." (PMID 28423539, 2017). "This increase may have caused increased IL-6 expression and secretion, which in turn leads to activation of STAT3 and a subsequent upregulation of downstream targets that promote tumorigenesis and tumor cell proliferation." (PMID 28350804, 2017). "In addition, STAT3, beyond its oncogenic role at the tumor cell level, has potent immunosuppressive effects in the tumor microenvironment, affecting the function of multiple lymphoid and myeloid cell types including dendritic cells (DCs)." (PMID 28435516, 2017). "This suggests a paracrine mode of STAT3 activation at the tumor invasive margin." (PMID 28895886, 2017). "Taken together, our results indicated that nifuroxazide could effectively inhibit tumor metastasis by mediating Stat3 pathway and it might have a therapeutic potential for the treatment of CRC." (PMID 28055016, 2017). "Similarly, STAT3 decoy oligonucleotide has been reported to decrease proliferation, migration and tubule formation of endothelial cells in vitro and to inhibit tumor angiogenesis in murine HNSCC xenografts." (PMID 28915663, 2017). "STAT3 is one of the central players in this tumor-induced immune deregulation." (PMID 28346397, 2017). "In this study, we showed that p-STAT3 is correlated with tumor grade in HNSCC." (PMID 28270740, 2017). "Hypoxia and inflammatory factors activate STAT3 to promote tumor angiogenesis." (PMID 28978186, 2017). "Furthermore, phosphorylated JAK and STAT3 in tumor tissue were both reduced after fucoidan treatment, and promoter activation of STAT3-regulated genes, such as VEGF, Bcl-xL and Cyclin D1, was also significantly reduced after treatment." (PMID 28764703, 2017). "In HPV-driven carcinogenesis STAT3 is not only activated in the tumor microenvironment." (PMID 28895886, 2017). "Radiation upregulated PD-L1 expression in tumor cells through IFN-γ/STAT3 signaling, which could facilitate therapeutic action of anti-PD-L1." (PMID 28465485, 2017). "Indeed, by targeting either TRIM8 or STAT3, researchers would be able to disrupt their positive feedback loop and attenuate the self-renewal capacity and tumour propagation of GBM." (PMID 29182544, 2017). "Furthermore, the STAT3 inhibitor effectively blocked the growth of patient-derived tumor xenografts that harbored phosphorylated STAT3, but acted less effective on the xenografts derived from primary tumors that contained low levels of activated STAT3." (PMID 29179470, 2017). "We postulate that tumor cells may acquire migratory phenotype through the IL-6/IL-6R/STAT3 axis, and potent chemokines, such as CXCL8, initiate the actual cellular movement to a specific direction." (PMID 29245982, 2017). "Here, using both in vitro and in vivo colon carcinoma models, we found that fasting could suppress M2 polarization of TAMs through inactivating JAK1/STAT3 in the tumor microenvironment and therefore inhibit tumor cell growth." (PMID 29088814, 2017). "STAT3 is ubiquitously expressed in most tissues, however, constitutively active STAT3 may contributes to tumor progression and metastasis in diverse cell types." (PMID 29212252, 2017). "Likewise, evaluation of STAT3 protein in PC tissues by Western blotting showed a constitutively activated STAT3 (pY705) in all tumor grades compared to the matched normal sections." (PMID 29156772, 2017). "However, the prolonged STAT3 activation in cells of the tumor microenvironment preserves their production, thus resulting in differentiation and accumulation of MDSCs." (PMID 28824627, 2017).